OR10H4 (olfactory receptor family 10 subfamily H member 4)
Description:
Odorant receptor.
Synonyms: OR19-28
Tractability: Antibody: UniProt places it where antibodies can reach, with medium confidence; UniProt predicts a signal peptide or a membrane-spanning region; its Gene Ontology location is reachable by antibodies, with medium confidence.
Gene: Protein-coding gene on chromosome 19 (15,944,299 to 15,950,350, forward strand). Ensembl gene ENSG00000176231.
Subcellular location: Cell membrane
Pathways (Reactome):
Sensory Perception: Expression and translocation of olfactory receptors
Gene Ontology:
Molecular function: olfactory receptor activity; G protein-coupled receptor activity
Biological process: detection of chemical stimulus involved in sensory perception of smell; G protein-coupled receptor signaling pathway
Cellular component: plasma membrane; membrane
Genetic constraint (gnomAD): Loss-of-function variants: 10 observed, 11.08 expected, observed/expected ratio (o/e) 0.9, 90% interval 0.56 to 1.52. The upper end of that interval is the gene's LOEUF score, 1.52, which puts it in group 6 of 6, group 1 being the genes least tolerant of losing a copy. Missense variants: 395 observed, 406.72 expected, observed/expected ratio (o/e) 0.97, 90% interval 0.89 to 1.05. Synonymous variants: 160 observed, 157.81 expected, observed/expected ratio (o/e) 1.01, 90% interval 0.89 to 1.16.
Homologues: Orthologues: chimpanzee OR10H4 (97% identical), dog OR10H4C (82% identical), dog OR10H1E (80% identical), mouse Or10h28 (76% identical). Paralogues in human: OR10H3 (90% identical), OR6B3 (42% identical), OR6B2 (41% identical), OR10V1 (41% identical), OR8B4 (41% identical), OR8H1 (41% identical), OR8H2 (40% identical), OR5D18 (40% identical), OR5I1 (40% identical), OR8U3 (40% identical), OR9I1 (40% identical), OR8H3 (40% identical), and 84 more.